LINC01029 (long independently transcribed non-coding RNA 1029)
Gene: Long non-coding RNA gene on chromosome 18 (77,924,025 to 77,993,759, reverse strand). Ensembl gene ENSG00000265843.
Diseases named in the same sentence as LINC01029 in open-access papers:
LINC01029 is named in the same sentence as 1 disease in open-access papers, as found by Europe PMC text mining. Sharing a sentence is not in itself a finding about the gene and the disease.
LINC01029 shares sentences with these, for which no sentence is quoted: schizophrenia (1 paper).